CD44 (CD44 molecule (IN blood group))
Diseases named in the same sentence as CD44 in open-access papers (continued):
Sharing a sentence is not in itself a finding about the gene and the disease.
lung carcinoma (continued). "Moreover, CD44 KD led to a reduction in HA matrix formation surrounding lung cancer cells, further affirming the functional importance of CD44 in the HA network." (PMID 40178908, 2025). "Furthermore, ZEB1 facilitates alternative splicing and isoform expression of CD44, an HA receptor, and CD44 knockdown suppresses the motility and invasiveness of lung cancer cells." (PMID 40178908, 2025). "Several marker genes including CD133, CD44, and CD90 are associated with CSCs in lung cancer." (PMID 40109864, 2025). "It has been proved deglycosylation by neuraminidase induced CD44-HA binding in human lung cancer cell lines, but whether NEU1 is the key neuraminidase for HA deglycosylation in lung cancer remains unclear." (PMID 38500102, 2024). "For instance, tobacco smoke and related carcinogens, such as benzo[a]pyrene (BaP), may induce PD-L1 expression in lung cancers and CD44 expression in head and neck cancers." (PMID 39148690, 2024). "In addition, in the EGFR wild‐type non‐small cell lung cancer cell line H460, knocking down CD44 by siRNA has been found to reduce cell growth and induce cell apoptosis." (PMID 38783892, 2024). "Trifluoperazine treatment of lung cancer stem cells reduced the sphere-forming ability of lung cancer cells and down-regulated CD44 and CD133 expression, and trifluoperazine in combination with gefitinib or cisplatin effectively controlled drug resistance in lung cancer cells." (PMID 37674202, 2023). "Some of the analyzed variants (e.g., OPN rs1126772 or CD44 rs187116) have never been investigated in lung cancer before." (PMID 38067149, 2023). "Moreover, a regulator named SFPQ was shown to be overexpressed and to promote lung cancer malignancy via CD44 v6 expression." (PMID 38069324, 2023). "CD133 and CD44 are two commonly used markers for lung cancer stemness." (PMID 37752152, 2023). "Some ADC drugs targeting CD44, such as conjugation of hyaluronan with irinotecan, cisplatin, and apoferritin, are effective in reducing or even eliminating stem cells in lung cancer." (PMID 35719973, 2022). "Furthermore, levels of HA signaling pathway mediators and regulators of HA synthesis such as RHAMM, CD44, hyaluronidases, and hyaluronan synthases have shown prognostic potential in lung cancer warranting further validation." (PMID 36342462, 2022). "Understanding the relationship between SFPQ and CD44 may help to elucidate the pathological mechanism of NSC lung cancer." (PMID 35707369, 2022). "Furthermore, there was a strong inverse correlation between Sp1 and CD44 levels in clinical lung cancer specimens." (PMID 35034634, 2022). "In conclusion, the CD44+ lung cancer cells were more resistant to cisplatin than the CD44− cells." (PMID 35806135, 2022). "CD44 could promote PD-L1 expression in breast and lung cancers, which suggests that it may indirectly affect the immune infiltration of tumours." (PMID 36316684, 2022). "(2019)have developed dual-targeting nanomicelles with CD133 and CD44 aptamers for lung cancer." (PMID 35191342, 2022). "Furthermore, our study added a new insight regarding the role of CD44 in lung cancer metastasis that CD44 can promote lung cancer metastasis through the ERK–ZEB1 pathway." (PMID 34439211, 2021). "It has been reported in pancreatic and lung cancer cells that stimulation with growth factors induces the translocation of p32 to membrane lipid rafts where its interaction with CD44 favors the autophosphorylation and activation of Receptor Tyrosine Kinases (RTKs)." (PMID 34136383, 2021). "In this study, we conclude that CD44 promotes lung cancer cell metastasis in vitro and in vivo." (PMID 34439211, 2021).
lung carcinoma (continued). "Authors also performed a proliferation and self-renewal test with TP and CD44 siRNA on putative lung cancer stem cells and confirmed their results with NSCLC cells comparing the effect of TP to the effects of transfection of NSCLC cells with HAS2, CD44, or RHAMM siRNA." (PMID 33981532, 2021). "As IHC results revealed that CD44 might play a role in lung cancer metastasis, we further evaluated the expression of CD44 in different cancer cell lines and found that there was a positive correlation between CD44 expression and cancer cell invasion ability." (PMID 34439211, 2021). "In summary, our in vitro and clinical results indicate that CD44 may be a potential prognostic and therapeutic marker for lung cancer patients." (PMID 34439211, 2021). "It has been reported that lung cancer cells expressing CD44 have enriched CSC properties." (PMID 34949193, 2021). "We also investigated the effect of CD44 expression on lung cancer cell proliferation." (PMID 34439211, 2021). "Moreover, in vitro studies have demonstrated the enhanced uptake of rhodamine labeled HA/PEI-decorated PLGA NPs in CD44+ lung cancer cells and improved DTX cytotoxic activity, compared to the free drug." (PMID 34683830, 2021). "In summary, this study suggests that CD44 may be a potential prognostic marker and therapeutic target for lung cancer patients." (PMID 34439211, 2021). "A previous study studying HA CD44/RHAMM pathway in lung cancer cells only knocked down HAS2 and HAS3 as us, we suggested they might also come across the same issue." (PMID 33407495, 2021). "Flow cytometry analysis was carried out to isolate CD133 or CD44 positive lung cancer cells." (PMID 34949193, 2021). "Additionally, in our clinical study using primary lung tumors and paired lymph nodes, we were able to conclude that CD44 expression is positively correlated with lung cancer metastasis to regional lymph nodes." (PMID 34439211, 2021). "Other research indicated that targeting the HA/CD44 signaling pathway could be a promising approach for the prevention and therapy of lung cancer." (PMID 35154001, 2021). "We report that CD44 cleavage in A549 lung cancer cells and other cells is promoted by transforming growth factor-beta (TGFβ) in a manner that is dependent on ubiquitin ligase tumor necrosis factor receptor-associated factor 4 or 6 (TRAF4 or TRAF6, respectively)." (PMID 33804427, 2021). "Furthermore, ERK inhibition suppressed the migration and invasion abilities of CD44-overexpressing lung cancer cells." (PMID 34439211, 2021). "Moreover, IHC results from lung cancer patient tissue samples showed that CD44 expression was high in metastatic lymph nodes." (PMID 34439211, 2021). "Additionally, OPN contributes to the migration of lung cancer cells through combining with alpha v beta 3 integrin or adhensive glycoprotein receptor CD44 by activating the PI3K pathway." (PMID 32909189, 2021). "Again, HA is implicated in EMT through EGF or TGF-β1 signaling in lung cancer cell line A549, where TGF-β1 upregulates HAS1, HAS2, and HAS3 expressions and augments CD44 expression interacts with EGFR, leading to the activation of the downstream signaling AKT and ERK pathways." (PMID 34976811, 2021). "Consistent with this, other groups have reported that in pancreatic and lung cancer cells, growth factors induce the translocation of p32 to membrane lipid rafts where its interaction with CD44 favors the autophosphorylation and activation of Receptor Tyrosine Kinases (RTKs)." (PMID 34136383, 2021). "This study provided evidence that CD44 may be a possible therapeutic target to decrease lung cancer metastasis." (PMID 34439211, 2021). "Lung cancer cells expressing CD44 have been reported to be enriched for stem-like properties." (PMID 33372595, 2020). "CD44 was directly targeted by miR-485 in A549-cisplatin resistant lung cancer cells." (PMID 32290543, 2020). "CD44 has been identified as a crucial surface marker indicating CSC in lung cancer." (PMID 33372595, 2020).
lung carcinoma (continued). "Blocking the interaction between HA and CD44 reduced viability of A549 human lung cancer cells." (PMID 32592613, 2020). "Moreover, lung cancer stem cells express “stemness”-related biomarkers, such as CD44, CD24, CA133, CD13, CD90, ABCG2, SOX2, and EPCAM." (PMID 32849930, 2020). "Moreover, EGCG can upregulate miR-485, which targets CD44 in cisplatin-resistant lung cancer cells, thus weakening lung cancer stemness." (PMID 33066509, 2020). "Moreover, the authors modified the apoferritin by HA to target and kill the cancer cells (embryonic lung MRC-5 cells and lung cancer A549 cells) upon binding to the HA-receptor CD44." (PMID 31035440, 2019). "Other studies have provided some evidence that the membrane receptor glycoprotein, CD44, able to bind hyaluronic acid, could represent a marker of lung cancer initiating cells." (PMID 30060526, 2018). "Knock-down of ETS-1 inhibited the S1P-induced CD44 expression and human lung cancer cell migration." (PMID 29747682, 2018). "Yet, several surface markers have been proposed in the literature including CD24 for pancreatic and lung cancer, CD44 for breast, liver and head and neck cancers, CD133 (or Prominin) used for brain, colorectal, lung and liver cancers, and EpCAM/ESA for colorectal, and pancreatic cancers." (PMID 29391537, 2018). "CD44 also contributes to cell survival via regulating Fas in lung cancer cells." (PMID 29747682, 2018). "The knockdown of SALL4 expression could suppress spheroid formation and the expression of lung cancer stem cell marker CD44." (PMID 29691367, 2018). "Recent studies suggested that CD44 appeared to be a potential lung cancer stem cell marker." (PMID 29691367, 2018). "Since triptolide suppressed the expression of CD44, another marker for cancer stem cells, we sought to determine, using pulmosphere assay, if the drug inhibits the proliferation and self-renewal of putative lung cancer stem cells." (PMID 28460475, 2017). "Hence, CD44 has been proposed to be used for the isolation and enrichment of CSCs in lung cancers including MPM." (PMID 28403901, 2017). "CD44 expression is characteristic of different cancers, including lung cancer." (PMID 28290155, 2017). "Our study revealed that ITGβ3 and CD44 expression levels determine whether OPN-a inhibits or enhances growth in lung cancer cells." (PMID 27487131, 2016). "In addition, CD133+/hi or CD44+/hi cells sorted from four different lung cancer cells also showed higher activation of CaMKIIγ than did CD133−/low or CD44−/low cells." (PMID 25965829, 2015). "Taken together, results lead us to hypothesize that biodegradable NPs coated with a PEI/HA shell represent a very promising system to treat CD44 overexpressing lung cancer." (PMID 25888948, 2015). "Indeed, isoform-specific expression of genes such as VEGF, p63, p73, and CD44 has been correlated with discrete pathologies and survival in lung cancer patients." (PMID 26046767, 2015). "Much research has been done on CD44 expression in lung cancer." (PMID 24699516, 2014). "Interestingly, we found a correlation between the antigens CD133 and CD44 expression on the individual lung cancer cell lines tested." (PMID 23738757, 2013). "If this hypothesis holds to be true, then we may be in a position to offer common CD44-biomarker guided therapeutics across lung cancer subtypes." (PMID 24019906, 2013). "The differences observed in CD133 and CD44 expression cannot be explained by which type of primary lung cancer the cell line originated from, since both the HTB-182 and LC-42 were derived from squamous cell carcinoma while the EKVX and SELS cells were derived from adenocarcinoma." (PMID 23738757, 2013). "The purpose of this study is to investigate the differential expression and clinical significance of seven stem-cell-associated markers (Bmi1, CD133, CD44, Sox2, Nanog, OCT4 and Msi2) in lung cancer, providing new targets for the diagnosis and treatment of lung cancer." (PMID 23683495, 2013).
lung carcinoma (continued). "In non–small-cell lung cancer, cells expressing CD44 are enriched for stem cell-like properties." (PMID 23651443, 2013). "A large number of CD44 molecules are also expressed in lung cancer cells." (PMID 22605928, 2012). "The expression pattern of CD44 was also characterized in clinical lung cancers." (PMID 21124918, 2010). "In summary, this study has provided evidence that amongst reported CSC markers such as CD133, ALDH, CXCR4, ABCG2, ESA and side population staining, CD44 could be a potentially useful marker for lung cancers." (PMID 21124918, 2010). "Moreover, PCA-BSA@FA-NPs treatment led to reduced CD44 levels, which may inhibit lung cancer angiogenesis and metastasis." (PMID 40670469, 2025). "Additionally, we correlated AKT activation to CD44 expression in 175 lung cancer patient samples." (PMID 35853934, 2022). "In this study, we found that E2 increased RNF4 to reduce the Sp1 level, thereby enhancing CD44 expression through downregulation of miRNAs, leading to a poor prognosis in young women with lung cancer; this finding may be beneficial for developing therapeutic strategies in the future." (PMID 35034634, 2022). "Cluster of Differentiation-44 (CD44) is a glycoprotein that plays a key role in multiple mammalian cell biological functions, and overexpressed CD44 is found in some tumors such as lung cancer.The potential role of CD44 receptor biology in CS-induced lung injury mechanisms remains largely unknown." (PMID 35562995, 2022). "Collectively, our phosphoproteomic analysis of lung-cancer cells resistant to FGFR1 inhibitor provides a large data library of resistance-associated phosphorylation patterns and leads to the proposal of a common resistance pathway comprising CD44, PAK1 and AKT activation." (PMID 35853934, 2022). "Furthermore, alternative splicing of CD44 mRNA by ESRP1 enhances metastasis in lung cancer." (PMID 32467669, 2020). "Hence, based on the western blot results, we predicted that the knockdown of BRD4 could decrease the expression level of CD44, jointly inhibiting the lung cancer cell migration and invasion." (PMID 31621555, 2020). "Besides, CD133 and CD44 were also specific markers for lung cancer-initiating cells." (PMID 32998391, 2020). "Additionally, primary tumor samples from breast and lung cancer patients expressed high levels of PD-L1 correlating with CD44 positivity, suggesting that CD44 regulation of PD-L1 expression observed in vitro could be similar to that of an in vivo human tumor." (PMID 33193345, 2020). "One example is the use of other cell receptors, such as CD44, for which hyaluronic acid is a specific ligand, which are also described to be also overexpressed in many solid tumor cells including breast, melanoma and lung cancer, like the A549 cell model used in this study." (PMID 27788212, 2016). "Thus, OPN-a, integrin β3, and CD44 interact to affect lung cancer cell growth, and this study may aid in the development of cancer treatment strategies involving these molecules." (PMID 27487131, 2016). "Hence, Bmi1, CD44 and CD133 are poor diagnostic markers for lung cancer." (PMID 23683495, 2013). "CD44, GIMAP4, CD69, and CCL4L2 were among the most relevant contributing markers defining the predictive ML signatures on lung cancer samples." (PMID 40989699, 2025). "Treatment of the 3D organoid cell population with SM-3 resulted in a significant reduction in the levels of stem cell markers (CD133 and CD44) and stem cell transcription factors (OCT-4 and SOX2) in lung cancer organoids." (PMID 40287470, 2025). "At the same time, a subgroup of cells that highly express CD44 and CD133, two common surface markers for lung cancer stem cells, was selected with flow cytometry assays and detected for JMJD6 positivity." (PMID 41320721, 2025). "In our investigation, we observed that excessive TNFRSF21 expression stimulated lung cancer stem cell characteristics by promoting CD133 and CD44 mRNA expression." (PMID 40109864, 2025).
lung carcinoma (continued). "We further found that the expression of TSG6, CD44, CD68, and CD163 (marker of TAMs) is elevated in metastatic lung cancer tissues of mice driven by active PLK1." (PMID 40860188, 2025). "Our analysis of collected lung cancer specimens revealed elevated expression levels of DNMT1, CD44, and SOS1 in certain NSCLC tissues, establishing a positive correlation between DNMT1 and SOS1 in the progression of NSCLC." (PMID 38622665, 2024). "Our recent studies also indicated that USP24 can regulate CD44, which is also involved in the ECM of lung cancer." (PMID 38491202, 2024). "The results showed that more CD44-positive human lung cancer cells grew in lv-KCTD21-AS1-treated groups, but relatively fewer CD44-positive cancer cells were revealed in the siRNA-KCTD21-AS1- or miR-519d-5p-treated groups compared with the controls." (PMID 38383737, 2024). "In a lung cancer setting, a mouse model of KRAS-induced lung adenocarcinoma and KRAS and CD44 expression were evaluated to determine the in vivo role of CD44 related to KRAS." (PMID 38672650, 2024). "Akt inhibition has been shown to decrease the expression of stem cell markers such as CD133, CD44, and ALDH and to reduce the proportion of CSCs in lung cancer cell lines and patient-derived xenografts." (PMID 38672078, 2024). "In lung cancer cells, the downregulation of CD133 and CD44 expression has been shown to reduce the number of tumor spheres formed in vitro and to decrease tumor growth in vivo." (PMID 38672078, 2024). "Based on our findings, we propose a model depicting regulation of cisplatin resistance in lung cancer cells by CK2, CD44, and IGFBP-3." (PMID 36766747, 2023). "For lung cancer, ALDH, CD44, Oct4, c-kit, and Nestin were shown to be some of the most frequently observed CSCs markers which promote tumor development." (PMID 37233697, 2023). "The levels of the Sp1-regulated candidate miRNAs targeting CD44, β-catenin and ALDH1, i.e., miR-3194-5p, miR-218-5p, miR-200-5p, miR-193a-5p, miR-182-5p and miR-135-5p, were studied in A549-T24 and E2-A549 lung cancer cells." (PMID 35034634, 2022). "Here, we further investigated the effects in freshly sorted lung cancer cells and found that the CD44+ population was more resistant to cisplatin than the CD44− population." (PMID 35806135, 2022). "The other genes, CD44, PPARD, and STAT1, were also observed to be highly upregulated in lung cancer samples compared to asthmatics and healthy controls." (PMID 35406434, 2022). "Co-inhibition of CD44, Pak1 or AKT together with FGFR1 (re-)sensitized resistant lung cancer cells to FGFR1-targeted therapy." (PMID 35853934, 2022). "In particular, the genes BCL3, CD44, PPARD, and STAT1 showed an increase in expression among the mixed group (asthmatics diagnosed with lung cancer) and lung cancer samples." (PMID 35406434, 2022). "The fold change in expression showed significant upregulation for the genes BCL3, CD44, PPARD, POSTN, and STAT1 in lung cancer patients compared to asthmatics." (PMID 35406434, 2022). "Analysis of the enriched genes derived from the pathway analysis identified seven genes expressed in both the asthma and lung cancer sets: BCL3, POSTN, PPARD, STAT1, MYC, CD44, and FOSB." (PMID 35406434, 2022). "CD44, a cell-surface adhesion receptor has been used, in combination with ALDH, to identify potential CSCs in lung cancer." (PMID 35053430, 2022). "Co-inhibition of AKT/FGFR1, CD44/FGFR1 or PAK1/FGFR1 sensitized ‘intrinsically resistant’ and ‘induced-resistant’ lung-cancer cells synergetically to FGFR1 inhibition." (PMID 35853934, 2022). "We found that CD44 and SSEA4 positive MSCs isolated from normal lung cells and NSC lung cancer cells showed the differences in proteomics and ingenuity pathways related to cell stemness, cell proliferation, and invasion." (PMID 35707369, 2022). "We discovered that EV uptake increase the expression of SPP1, CD44, and POSTN genes in lung cancer cells." (PMID 36424413, 2022).